MPO (myeloperoxidase)
Description:
Peroxidase that plays a central role in the host defense system of polymorphonuclear leukocytes by mediating both (1) formation of neutrophil extracellular trap (NETs) and (2) microbicidal activity. Promotes NET formation by mediating chromatin disassembly: translocates to the nucleus and specifically binds to nucleosomes, both as monomer and homodimer, leading to nucleosome unstacking and initial chromatin decondensation. Homodimers clash with one end of the nucleosomal DNA, leading to DNA unwrapping, initiating complete disassembly of nucleosomes and chromatin transformation into NETs in an ATP-independent manner. NETs, which are mainly composed of DNA fibers and globular proteins, are then extruded into the extracellular space by neutrophils to trap pathogens and release antimicrobial proteins to destroy them. Participates to the microbicidal activity against a wide range of organisms by acting as a peroxidase that catalyzes the formation of oxidants in presence of hydrogen peroxide. Mediates the formation of hypohalous acids, mainly hypochlorous acid (HOCl) in physiologic situations, that greatly enhance polymorphonuclear leukocyte microbicidal activity. In addition to hypochlorous acid, catalyzes formation of hypobromous acid (HOBr), hypoiodous acid (HOI) and hypothiocyanous acid (HOSCN). Also catalyzes oxidation of nitrite into the highly reactive nitrogen dioxide radical. Formation of oxidants are widely believed to be responsible for much of the anti-bactericidal activity of neutrophils. Oxidants, such as hypochlorous acid or nitrogen dioxide radical, can also oxidize amino acid residues on proteins and generate chlorination and nitration post-translational modifications, respectively. Chlorination and nitration of the lipid-free form of APOA1 impairs cholesterol transport. Superoxides generated by MPO can also promote dioxygenation of tryptophan residues on proteins. Also able to oxidize melatonin into N1-acetyl-N2-formyl-5-methoxykynuramine either in presence of hydrogen peroxide or superoxide. Oxidizes urate into 5-hydroxyisourate. Functions as a nitric oxide (NO) oxidase during inflammation, by catalytically consuming NO, impairing NO's ability to maintain vascular tone and function. May also mediate the proteolytic cleavage of alpha-1-microglobulin to form t-alpha-1-microglobulin, which potently inhibits oxidation of low-density lipoprotein particles and limits vascular damage. [Myeloperoxidase light chain]: Light chain of the mature myeloperoxidase. [Myeloperoxidase heavy chain]: Heavy chain of the mature myeloperoxidase. (Microbial infection) The peroxidase activity is inhibited by S.aureus peroxidase inhibitor SPIN that blocks substrate access to the catalytic heme.
Tractability: Small molecule: a drug acting on it is in phase 2 or 3 trials; a structure with a bound ligand is known; a high-quality ligand is known; it has a high-quality binding pocket; it belongs to a druggable protein family. Antibody: its Gene Ontology location is reachable by antibodies, with high confidence; UniProt predicts a signal peptide or a membrane-spanning region. PROTAC: its protein half-life has been measured; a small molecule that binds it is known.
Target class: Enzyme; Oxidoreductase
Gene: Protein-coding gene on chromosome 17 (58,269,855 to 58,280,935, reverse strand). Ensembl gene ENSG00000005381.
Subcellular location: Lysosome; Cytolytic granule; Cytoplasmic vesicle, phagosome; Secreted; Nucleus; Chromosome
Subcellular location (Human Protein Atlas): Vesicles; Nucleoplasm
Pathways (Reactome):
Immune System: Events associated with phagocytolytic activity of PMN cells; Neutrophil degranulation
Gene Ontology:
Molecular function: heparin binding; nucleosome binding; peroxidase activity; protein binding; protein-containing complex destabilizing activity; chromatin binding; heme binding; thiocyanate peroxidase activity
Biological process: hydrogen peroxide catabolic process; low-density lipoprotein particle remodeling; neutrophil extracellular trap formation; neutrophil-mediated killing of bacterium; neutrophil-mediated killing of fungus; neutrophil-mediated killing of symbiont cell; nucleosome disassembly; positive regulation of cholesterol import; defense response; defense response to bacterium; negative regulation of apoptotic process; response to oxidative stress; cellular oxidant detoxification; defense response to fungus; immune effector process; response to food; response to gold nanoparticle; response to lipopolysaccharide; response to mechanical stimulus; thiocyanate metabolic process
Cellular component: azurophil granule; extracellular exosome; extracellular region; neutrophil extracellular trap; nucleus; phagocytic vesicle; secretory granule; azurophil granule lumen; lysosome; phagocytic vesicle lumen; chromosome; cytolytic granule
Genetic constraint (gnomAD): Loss-of-function variants: 58 observed, 72.75 expected, observed/expected ratio (o/e) 0.8, 90% interval 0.64 to 0.99. The upper end of that interval is the gene's LOEUF score, 0.99, which puts it in group 4 of 6, group 1 being the genes least tolerant of losing a copy. Missense variants: 971 observed, 1,043.5 expected, observed/expected ratio (o/e) 0.93, 90% interval 0.88 to 0.98. Synonymous variants: 426 observed, 434.18 expected, observed/expected ratio (o/e) 0.98, 90% interval 0.91 to 1.06.
Homologues: Orthologues: chimpanzee MPO (99% identical), macaque MPO (96% identical), dog MPO (87% identical), guinea pig MPO (84% identical), rat Mpo (84% identical), pig MPO (83% identical), mouse Mpo (83% identical), rabbit MPO (83% identical), zebrafish epx (40% identical), Drosophila melanogaster Pxn (37% identical), Caenorhabditis elegans pxn-2 (36% identical), Caenorhabditis elegans pxn-1 (35% identical), and 5 more. Paralogues in human: EPX (67% identical), LPO (50% identical), TPO (42% identical), PXDN (41% identical), PXDNL (37% identical).
Diseases named in the same sentence as MPO in open-access papers:
MPO is named in the same sentence as 852 diseases in open-access papers, as found by Europe PMC text mining. Sharing a sentence is not in itself a finding about the gene and the disease. The quoted sentences say what the papers report.
colitis (825 papers, 2006 to 2026). Inflammation of the colon. "NETs in the gut and/or blood have been implicated in IBD pathogenesis, and murine colitis models recapitulate NETs formation in inflamed mucosa, characterized by DNA backbones decorated with neutrophil elastase, MPO, and H3cit19,20." (PMID 40813467, 2025). "Concordantly, PM suppressed colitis-associated biomarkers of oxidative injury—notably reducing myeloperoxidase (MPO) (reflecting neutrophil infiltration) and malondialdehyde (MDA) (indicating lipid peroxidation)." (PMID 41303686, 2025). "The results show that the Mcpt-4-deficiency exacerbated colitis, as reflected by the significantly greater weight loss, higher histological scores, elevated levels of myeloperoxidase and most of determined cytokines." (PMID 40697820, 2025). "As neutrophil influx is a hallmark of acute DSS colitis pathophysiology, we determined myeloperoxidase (MPO) activity in colonic homogenates as a readout for neutrophil activity." (PMID 39179175, 2024). "Wild type (Wt) and MPO-deficient mice were treated with dextran sodium sulphate (DSS) in a chronic model of experimental colitis with three acute cycles of DSS-induced colitis over 63 days, emulating IBD relapse and remission cycles." (PMID 38673843, 2024). "In a previous study, IL-6 deficiency promoted the development of colitis by recruiting more neutrophils, which secreted MPO and destroyed the intestinal epithelium." (PMID 39275347, 2024). "The reduced severity of colitis in MC-170073-treated mice given DSS was also associated with lower levels of both colonic MPO and the proinflammatory cytokines IL-1β, IL-6, and TNF-α." (PMID 38713616, 2024). "Using the acute and chronic dextran sodium sulfate model of murine colitis, we demonstrated that MPO-deficient mice experienced less inflammation and more rapidly resolved colitis relative to wild-type controls." (PMID 39133648, 2024). "As an initial series of experiments to define the contribution of MPO to colitis, we examined the severity and resolution of acute colitis in wild-type (WT) and MPO-deficient (MPO-KO) mice." (PMID 39133648, 2024). "On day 7, when peak weight loss is typically observed in the DSS-induced colitis model, the WT mice had on average approximately 10% weight loss compared with approximately 4% in the MPO-KO mice (P < 0.001)." (PMID 39133648, 2024). "The results showed that cucurbitacin IIb alleviated colitis symptoms including body weight loss, an increase in the disease activity index, and elevated levels of myeloperoxidase and eosinophil peroxidase content." (PMID 39347394, 2024). "Studies have also demonstrated that MPO activity is increased in response to heat stress and is associated with intestinal permeability in piglets and with colitis in a piglet model." (PMID 38674829, 2024). "Studies have shown that the level of MPO in the tissues of patients with colitis is closely related to the severity of inflammation, and high levels of MPO activity are associated with the activity and deterioration of the disease." (PMID 38790796, 2024). "Ocimum basilicum L. essential oil, for instance, has been shown to mitigate tissue damage and myeloperoxidase (MPO) activity caused by colitis." (PMID 38831882, 2024). "Exposed IS caused colitis in mice, decreasing colon length and IL-10 levels and increasing myeloperoxidase, TNF-α, IL-1β, and IL-6 levels in the colon." (PMID 39519543, 2024). "Recovery from the disease for all mice subjected to the induction of experimental colitis was associated with a decline in local NO production and MPO activity compared to the peak of the disease." (PMID 38892639, 2024). "In our study, colonic MPO activity was significantly increased in vehicle-treated colitis compared to the control group (p < 0.001), which was associated with colon inflammation." (PMID 39682761, 2024).
colitis (continued). "Hyperactive inflammation cells, particularly neutrophils and macrophages, generate some pro-inflammatory factors, ROS, MPO and nitrogen metabolites, which are related to the pathogenic mechanism of colitis." (PMID 37324477, 2023). "The colon tissue-associated MPO activity provides quantitative data on neutrophil infiltration that displays the severity of colitis." (PMID 37127609, 2023). "Exposure to IS also caused colitis in mice: it shortened colon and increased colonic myeloperoxidase, TNF-α, and IL-6 expression and NF-κB+CD11c+ cell (dendritic and macrophage cells) number, resulting in colonic inflammation." (PMID 36926604, 2023). "In the present study, animals with seven days of colitis induction had greater macroscopic and microscopic damage, neutrophilic infiltration, and loss of mucosal architecture and higher MPO levels than the control group." (PMID 37909497, 2023). "Increased MPO activity has been associated with colitis severity and can be used as a biomarker of inflammation." (PMID 35935215, 2022). "Pathogenic bacteria of colitis such as Shigella, Oscillospira and Xenorhabdus, which were negatively correlated with most SCFAs, were significantly positively correlated with MPO, TNF-α, IL-1β, IL-6, IL-17, and IgE (P ≤ 0.05)." (PMID 36451737, 2022). "FMTs from patients with IBD/D+ or IBD/D− caused IBD-like colitis in the transplanted mice: they increased the myeloperoxidase activity, IL-1β and IL-6 expression, and NF-κB+/CD11c+ cell population in the colon." (PMID 34650107, 2021). "The FMTs from patients with IBD/D+ or IBD/D− all caused colitis in mice: they significantly induced colon shortening; upregulated myeloperoxidase activity, IL-1β and IL-6 expression and increased the NF-κB+/CD11c+ cell population in the colon." (PMID 34650107, 2021). "In agreement with our previous data, DNBS-induced colitis was associated with a significant increase in MPO activity." (PMID 33672574, 2021). "This was associated with the gradual development of colitis as evidenced by a significant increase in inflammatory indices assessed by colonoscopy, macroscopy, microscopy, MPO activity and colonic weight/length ratio." (PMID 34248633, 2021). "Data presented on colitis phenotype (i.e., weight loss, macroscopic tissue damage and MPO activity) are a representative set of data from the rats used for AEA and 2-AG analysis, but these effects were consistent across all experimental cohorts." (PMID 33452437, 2021). "MPO is an enzyme contained within the granules of neutrophils, and increased MPO activity is associated with severe colitis." (PMID 33946346, 2021). "Paenalcaligenes hominis treatment also caused colitis, including colon shortening and an increase in the myeloperoxidase activity, IL-1β expression, and NF-κB+/CD11c+ cell population in the colon." (PMID 32669127, 2020). "We found that intestine epithelium-specific Smarcad1-KO protects the mice from DSS-induced colitis, reducing the response in terms of weight loss, disease activity index, MPO+ cell recruitment, and gene expression response." (PMID 32160911, 2020). "Exposure to EC also induced colitis in mice, causing colon shortening and increased myeloperoxidase activity, TNF-α and IL-6 expression, NF-κB activation, and infiltration of NF-κB/CD11c+ cells (activated DCs and macrophages) in the colon." (PMID 32224881, 2020). "Excessive MPO activity is involved in the pathogenesis of inflammatory bowel disease and in the promotion of colitis-associated cancer." (PMID 33167555, 2020). "Previous results of our team demonstrated a significant increase in the colon activity of MPO in animals with colitis caused by LPS or TNBS." (PMID 32365955, 2020). "Acute sleep deprivation increased disease severity measured with tissue myeloperoxidase and chronic intermittent sleep deprivation caused both worsening of histological as well as clinical manifestations of colitis." (PMID 32927760, 2020).
colitis (continued). "IS exposure-induced colitis caused colon shortening and increased myeloperoxidase activity, TNF-α and IL-6 expression, and NF-κB activation in the colon." (PMID 32224881, 2020). "These bacteria additionally caused colitis, including colon shortening, myeloperoxidase activity, and IL-1β expression in the colon." (PMID 32669127, 2020). "DSS induced more severe colitis in AMPKαfl/fl-Lyz2-Cre mice, as assessed by body weight loss, increases in colon weight/unit length, and MPO levels, than in WT mice." (PMID 32365634, 2020). "Anthocyanin fraction from the tubers of purple yam down-regulated TNF-α, IFN-γ, and inflammation-associated ROS-producing enzyme myeloperoxidase (MPO) in mice treated with TNBS to induce colitis." (PMID 31137777, 2019). "Exposure to IS alone significantly caused colitis: It induced colon shortening, colonic myeloperoxidase activity, proinflammatory cytokine IL-6 and IL-1β expression, and NF-κB activation, and COX-2 expression." (PMID 30979031, 2019). "Another study showed that Lactobacillus crispatus M247 ameliorates the outcome of DSS colitis in a dose‐dependent manner, reducing colonic MPO activity and body weight loss in 108 and 106 bacteria‐treated mice." (PMID 31572604, 2019). "Curcumin has been shown to decrease intestinal inflammatory disease-associated MPO activity in animal models of colitis, thereby limiting oxidative tissue damage." (PMID 31003422, 2019). "In a DSS-induced colitis mice model, orally administered blueberry extract attenuated the development of colitis, which was associated with markedly attenuated colonic MPO activity, decreased MDA in the colon, increased serum levels of SOD and catalase." (PMID 31212794, 2019). "In the TNBS colitis model, colonic damage was associated with a high level of MPO (80 ng/mg of total proteins), a marker of neutrophil infiltration into the inflamed tissue." (PMID 30592734, 2018). "In the presented study, induction of colitis with TNBS caused an increase in mucosal MPO activity, whereas obestatin treatment partially, but significantly, reversed this effect." (PMID 29865176, 2018). "Our current study showed that induction of colitis by acetic acid enema is associated with an increase in mucosal interleukin-1β concentration and activity of myeloperoxidase in the colon." (PMID 28538694, 2017). "Rats fed a diet containing capric and lauric acid followed by DSS-induced colitis, developed worse colitis associated with a higher colonic myeloperoxidase activity and a pro-inflammatory cytokine profile as well as a reduction in goblet cells." (PMID 28804483, 2017). "Niacin attenuated the severity of colitis as demonstrated by a decrease in weight loss, colonic wet weight and MPO activity." (PMID 28769047, 2017). "MPO activity, a hallmark of colonic inflammation, was up-regulated in colons of rats with colitis indicating massive leukocyte infiltration into the colon as verified by the histological examination." (PMID 28769047, 2017). "Induction of colitis caused more than a 3-fold increase in myeloperoxidase activity in colonic mucosa." (PMID 27433160, 2016). "Intraperitoneal administration of obestatin in animals with acetic acid-induced colitis caused a considerable decrease in colonic MPO activity." (PMID 26798415, 2016). "The repeated treatment caused severe colitis, concurrent with colon shortening, edema, and increase of myeloperoxidase activity." (PMID 27761147, 2016). "Measurement of MPO activity is directly associated with neutrophil content, thus used as a quantitative index of inflammation in colitis." (PMID 27029486, 2016). "Intrarectal injection of TNBS in MRC mice caused severe colitis, as well as colon shortening, edema, and increased myeloperoxidase activity." (PMID 27761147, 2016).